GARIN6 (golgi associated RAB2 interactor family member 6)
Synonyms: FAM71C; MGC39520
Tractability: No criterion of Open Targets' tractability assessment is met for any kind of drug.
Gene: Protein-coding gene on chromosome 12 (99,647,753 to 99,650,114, forward strand). Ensembl gene ENSG00000180219.
Gene Ontology:
Molecular function: protein binding
Genetic constraint (gnomAD): Loss-of-function variants: 8 observed, 12.7 expected, observed/expected ratio (o/e) 0.63, 90% interval 0.37 to 1.14. The upper end of that interval is the gene's LOEUF score, 1.14, which puts it in group 4 of 6, group 1 being the genes least tolerant of losing a copy. Missense variants: 313 observed, 318.85 expected, observed/expected ratio (o/e) 0.98, 90% interval 0.89 to 1.08. Synonymous variants: 112 observed, 117.05 expected, observed/expected ratio (o/e) 0.96, 90% interval 0.82 to 1.12.
Homologues: Orthologues: chimpanzee GARIN6 (98% identical), macaque GARIN6 (95% identical), dog GARIN6 (66% identical). Paralogues in human: GARIN4 (57% identical), GARIN3 (52% identical), GARIN2 (29% identical), GARIN5A (25% identical), GARIN5B (25% identical), GARIN1A (21% identical), GARIN1B (20% identical).